AR (androgen receptor)
Diseases named in the same sentence as AR in open-access papers (continued):
Sharing a sentence is not in itself a finding about the gene and the disease.
tumor (continued). "As expected from the much higher AR copy number in LuCaP 105CR vs. LuCaP 105 tumor tissue, the levels of full-length AR mRNA and protein were also higher." (PMID 37636316, 2023). "As the degradation of AR triggers the increase in eIF4E phosphorylation by Mnk1/2, combination of AR antagonists and mTOR inhibitors was effective in suppressing tumor growth." (PMID 36831540, 2023). "This AR ecDNA pattern also occurred in most nuclei from LuCaP 105 tumor cells grown in intact mice, but with lower signal intensity." (PMID 37636316, 2023). "Overall, these findings show that pharmacological inhibition of KDM5 family, downregulated the tumor-promoting transcriptome in AR-dependent PCa cells." (PMID 37152294, 2023). "Second, in addition to its role in DNA damage repair, PARP1 is also involved in transcriptional regulation as a potent modulator of AR function and inducer of AR activity, and thus is involved in tumor proliferation." (PMID 37810962, 2023). "All these data suggest that, in addition to effects on cell proliferation and death, AR activity promotes tumor malignancy by increasing migratory and invasive capacities in PC." (PMID 37894767, 2023). "The key genetic alterations during this conversion include: altered androgen receptor (AR), gene fusion, alteration of tumor suppressors, defective DNA repair mechanism." (PMID 38089408, 2023). "Some AR expression is beneficial for prognosis, too much expression, however, along with heightened activity, leads to enhanced tumor growth." (PMID 38067367, 2023). "As such, AR lowered both activity and stemness of tumor-infiltrating CD8+ T-cells in male mice, and castration combined with PDL1 Ab synergistically dampened tumor growth." (PMID 37686465, 2023). "In this study, we aimed to reveal the effects of AR and NKX3.1 loss on ROS-induced DNA damage level and DDR mechanisms under oxidant and inflammatory conditions of tumor cells." (PMID 38155939, 2023). "The SPOP protein is involved in the ubiquitination and consequent proteasomal degradation of target proteins; in PC, SPOP acts as a tumor suppressor by targeting several proteins, including AR, SRC3, and BRD4." (PMID 37894312, 2023). "Fatty acid synthase also reprograms androgen-dependent and castration-resistant AR+ PCa models; thus, it can serve as a target that can potentially affect tumor aggressiveness." (PMID 35736421, 2022). "Hypoactivation of estrogen receptor (ER) and hyperactivation of Hedgehog and PI3K/AKT/mTOR signaling cascades are involved in a transition to neoplasia, while the decreased activity of androgen receptor (AR) and Wnt pathways contribute to disease progression." (PMID 36497095, 2022). "The androgen receptor is expressed exclusively in the nucleus of prostate cells, which has been confirmed both in healthy prostate tissue and in tissue with benign hyperplasia." (PMID 35055079, 2022). "A phase II study has been established in patients with AR-positive triple-negative tumor cells who have previously been treated with standard therapeutic regimens to evaluate its androgen blocking activity." (PMID 36612226, 2022). "Consistent with this, a subsequent study of AR isoform mRNA levels in circulating tumor cells (CTCs) showed that AR-V7 mRNA levels were equivalent to or higher than the AR mRNA levels in many AR-V7 negative CTCs10." (PMID 35354884, 2022). "The investigation demonstrated UroA to inhibit androgen receptor signalling axis to inhibit tumour growth of AR+ CEVEC’s amniocyte production (CaP)." (PMID 36079752, 2022). "In the neoadjuvant population, AR/estrogen receptor (ER) > 1.06 and residual tumor Ki67 > 23% had significantly worse DFS." (PMID 36556209, 2022).
tumor (continued). "Our findings suggest that AR sites specific to normal prostate epithelium (i.e., lost in tumor) serve to maintain prostate differentiation." (PMID 35509021, 2022). "Given the proximity of prostatic Gli1-lineage FB and basal cells, these data demonstrate a specific role for stromal AR in Gli1-lineage cells in regulating oncogenesis and tumor development initiated by prostatic basal epithelial cells." (PMID 36323713, 2022). "SPOP exerts its tumor suppressor roles mainly by promoting the degradation of its oncogenic substrates, such as AR, ERG, BRD4, and Nanog6,8,9." (PMID 35233061, 2022). "We suggest that hsa-miR-133a-3p and miR-1-3p act as tumor suppressor miRNAs in PCa because they interfere in the AR signaling pathway, the central pathway for PCa initiation and growth." (PMID 36387263, 2022). "Given that many of the phenotypic effects of AR are pro-tumorigenic and pro-tumor progression, much remains to be discovered regarding mechanisms by which AR negative TNBCs or QNBCs generally have poorer prognoses than AR-positive TNBCs." (PMID 35203574, 2022). "While highly recurrent state-specific alterations in AR chromatin profiles are gradually becoming established, inter-tumor heterogeneity of AR enhancer action remains largely unexplored." (PMID 36450752, 2022). "Higher AR expression was found in the enhancing tumor region and in the peritumoral area compared to the tumor core." (PMID 36361793, 2022). "Nevertheless, there still exists a therapeutic window for AR target therapy during the early stage of tumour progression." (PMID 35832549, 2022). "Outside of its impacts on the AR gene, tumor heterogeneity can also contribute to AR antagonist resistance through other pathways independent of AR." (PMID 35864113, 2022). "Since hypoxia is a frequent occurrence in solid tumor masses that has functional consequences for tumor progression, we were interested in examining the potential AR roles under hypoxia during RCC progression." (PMID 36397101, 2022). "Similar results are reported in HBV-induced HCC because a small chemical compound that can degrade androgen receptor (ASC-J9) successfully reduce tumor foci and volume in a mice model." (PMID 35860276, 2022). "Recently, truncated AR splice variants which lack a ligand binding domain and display constitutive activity even in low/no androgen conditions emerged as a possible mechanism for CRPC tumours to acquire ligand-independent AR signalling." (PMID 35568739, 2022). "4-OHT exhibits potent antitumor activity against AR-positive ER+ and ER− tumor cell lines (e.g. T47D, ZR-75, MDA-MB453) in vitro (unpublished data)." (PMID 37435469, 2022). "Based on further pathway analysis, we suggest that androgen receptor acts as a tumor suppressor in the BT-474 cells." (PMID 35568821, 2022). "Deletion of CHD1 in normal prostate cells altered the chromatin landscape and led to AR redistribution from lineage commitment regions to tumor-specific AR-bound regions." (PMID 35909568, 2022). "One meta-analysis shows that in early BC, AR is more likely to be co-expressed in ER+ over ER– tumours (74.8% vs. 31.8%, respectively)." (PMID 36376977, 2022). "Immunocompromised NSG mice bearing JN-DSRCT xenograft tumors treated with enzalutamide or AR-ASO significantly reduced tumor burden and improved survival with the same efficacy, compared to placebo or control groups during the first two months of treatment." (PMID 35650195, 2022). "To corroborate tumor viability data, we assessed the activation of apoptosis in AR-positive CRPC slices using RPPA." (PMID 35406510, 2022). "AR amplification was seen in a primary tumor specimen (SDC) that was resected from a hormone-naïve patient, indicating that the amplification was not a result of therapy-driven resistance." (PMID 36077692, 2022). "Accordingly, preclinical mouse models suggest that the AR exhibits both, proliferation-promoting and tumor-suppressive functions." (PMID 34667276, 2022).
tumor (continued). "As such, tumor cells with a luminal origin (AR+ and CK8+ cells, arrow) were found to invade the stromal compartment, supporting that focally invasive cancer develops in Arid1a-deficient prostates." (PMID 36435834, 2022). "iRGD-liposomes increase AR-ASO transfection in the tumor tissue and reduce androgen receptor expression." (PMID 35456655, 2022). "Consistently, the inhibition of these activators has been linked to reduced AR expression and PCA tumor growth in ex vivo analyses." (PMID 35954408, 2022). "A significant body of evidence shows that tumor hypoxia interferes with therapies that disrupt AR signaling or reduce androgen levels in PC." (PMID 36012111, 2022). "The role of AR likely depends on the subtype of BC as well as levels of circulating hormones and tumour microenvironment." (PMID 36376977, 2022). "Generally, ADT domesticates the M2-like polarization in a paracrine pattern by modulating other host cells, including tumor cells, which are not only limited by blocking the androgen/AR axis in macrophage-like cells." (PMID 36117852, 2022). "We also found overexpression of NE markers and downregulation of AR in TRIB2-OE cells in tumor xenografts in mice." (PMID 34973338, 2022). "AR target therapies trigger various cellular mechanisms that promote tumour evolution to bypass the dependency of androgens and/or AR." (PMID 35832549, 2022). "One of the cellular kinases activated through AR signaling is Src kinase, which is highly active in PCa and is involved in increasing malignant behaviors of the tumor cells." (PMID 37305018, 2022). "We observed that biochemical non-responders were more likely to harbour basal and luminal B tumours, and basal tumours exhibited lower AR activity than luminal tumours." (PMID 35091711, 2022). "AR gene disruption by CRISPR demolishes the expression of AR and AR-V7 and reduces LNCaP95 cell growth, supporting that AR-mediated signalling is still functional to promote tumour progression." (PMID 35832549, 2022). "Functional AR signaling is essential for survival and progression of PCa cells, especially in the early, hormone-sensitive stage of the tumor development." (PMID 35945234, 2022). "In our study, an orthotopic xenograft mouse model was used to evaluate AR expression and its inhibitory effects on tumor growth in vivo by lentivirus-mediated delivery of ATF4." (PMID 35013318, 2022). "When Di-PP/AR-siRNA/DTX reached the tumor site under the guidance of dimeric peptide, the nanocomplexes were first taken up by the tumor cells." (PMID 35631549, 2022). "The results of immunohistochemical staining further validated the higher level of AR protein in tumor tissues than in para-cancerous tissues of patients (Luminal A, Luminal B, and HER2)." (PMID 35880165, 2022). "Although ADT using several specific AR inhibitors blocks further tumor growth for some patients, most patients develop resistance to the treatment and subsequently develop to castration-resistant PCa (CRPC) associated with poor prognosis." (PMID 35865814, 2022). "It is well known that PCa is an androgen-dependent disease and activation of the androgen receptor (AR) is essential for tumour progression." (PMID 35215499, 2022). "Through molecular analyses of androgen receptor (AR) in GBM samples, we found that AR is commonly expressed in tumours of both sexes, but copy number alterations of the gene coding for AR are more frequent in females." (PMID 35661403, 2022). "Increased Chr X CN with AR amplification in primary PC tends to correlate with a higher tumor stage and Gleason score and poorer survival; however, the reported case number remains low." (PMID 35011998, 2022). "Herein, we utilized AR inhibitors to diminish PD-L1 expression on tumor cells via the novel ADAR2/circ_0001005/miR200a-3p signaling pathway, thereby enhancing NK cell-based immunotherapy." (PMID 35915245, 2022).
tumor (continued). "Blocking the SREBP-regulated metabolic pathway using statins has shown anti-tumor activity and, consequently, lowers AR signaling, which also controls cholesterol enzyme synthesis." (PMID 35736421, 2022). "CTCs isolated from patients with ABI- or ENZ-resistant metastasis showed amplification in the FOXA1 gene in > 30% of CRPC patients, pinpointing the crucial role of FOXA1 in AR regulation and tumor progression." (PMID 36176747, 2022). "Correlation of AR expression was examined with age, BMI, race, menopausal status, tumor grade, tumor size, and lymph node involvement, and response and outcomes." (PMID 35711833, 2022). "Using in vivo tissue grafting assays, we further examined co-inhibition of AR and Wnt signaling in hARtg+ tumor growth." (PMID 35902588, 2022). "In general, the correlation among AR-positive tumor samples was lower than in AR-null tumors, indicating the heterogeneous nature of the AR-positive population, similarly as observed in a recent study using AR-positive biopsies." (PMID 35406510, 2022). "Androgen receptor can promote tumour progression in desmoplastic small round cell tumour (DSRCT), an aggressive paediatric malignancy that predominantly affects young males." (PMID 35650195, 2022). "We also systematically correlate the m6A modification patterns with AR signaling, stemness, tumor immunogenicity and immune landscape in PCa." (PMID 35350771, 2022). "AR positivity, defined as AR ≥ 10%, accounts for approximately 30–35% of TNBC, and is associated with the LAR subtype, low tumour grade, lower risk of nodal involvement, and older age at diagnosis." (PMID 35954393, 2022). "Wild-type SPOP can promote the SRC-3 protein and then suppress AR transcriptional activity, thus functioning as a potential tumor suppressor." (PMID 36009418, 2022). "Currently, the next AR antagonist generation enzalutamide is being tested on AR-positive (AR+) tumours as a combined therapy with paclitaxel (NCT02689427)." (PMID 36077812, 2022). "In juvenile nasopharyngeal fibroma, the expression of AR is higher in tumor fibroblasts relative to the genital cells." (PMID 35517428, 2022). "Conversely, the activating PIK3CA mutations and increase in pAKT were abrogated by AR inhibition, which gave an exposition of the tumor-promoting action of AR." (PMID 35847875, 2022). "Despite this consolidated method the immunohistochemical analysis of AR expression still presents some gaps, such as the different cut offs proposed to classify AR-positive cases (i.e. 0% or 10% of immunopositive tumor cells)." (PMID 36111296, 2022). "Taken together, these data support the finding that AA inhibits tumour growth in vivo and counteracts AR target gene expression in the tumours." (PMID 35513564, 2022). "Collectively, these studies strengthen the view of CRPC as a transcriptionally addicted cancer type and highlight tCDKs as promising targets to prevent oncogenic AR signalling in relapsed tumours." (PMID 35568739, 2022). "The combination of AR antagonist bicalutamide with PI3K inhibitor GDC-0941 or the dual PI3K/mTOR inhibitor GDC-0980 reduced LAR xenograft tumor growth." (PMID 35768871, 2022). "Interfering with miR-130a-3p, overexpression of Erα/AR significantly inhibited CC cell proliferation and invasion, and antagomiR-130a reduced CC tumor size and weight in vivo." (PMID 35886904, 2022). "This already indicated low expression of AR‐V7 transcripts in the tumours measured in relation to total AR." (PMID 35661403, 2022). "AR is the classical target for PCa prevention and treatment, but more recently, estrogens and their receptors have also been involved in both tumor development and progression." (PMID 35457011, 2022). "NEPC and AR signaling scores were assessed in each tumor sample and compared between subgroups with high vs. unaltered FAP transcript levels." (PMID 35052475, 2022).
tumor (continued). "More interestingly, recent studies have described that, in metastatic CRPC and tumours that progress to AR-independency, epigenetic principal regulators are clearly altered, as well as key factor players in chromatin biology." (PMID 35205419, 2022). "Further support for this observation was seen in a retrospective study where patients with tumours expressing both AR and ER had a better prognosis than those with either AR or ER positivity." (PMID 36376977, 2022). "If the AR drives the progression of the CRPC tumour, does the AR rely on the castrate levels of androgens or act in a ligand-independent manner?" (PMID 35832549, 2022). "Investigating a potential interaction of CXCR4/CXCL12 axis with the AR, the most common therapeutic target for systemic therapies, IHC revealed AR expression in EC more affecting tumor areas compared to stromal tissue." (PMID 35717322, 2022). "This process is probably carried out until hypoxia occurs and AR expression declines, thus inhibiting tumor growth in the area." (PMID 36361793, 2022). "The expression of CXCL8 was positively associated with tumor stage, angiogenesis, and metastasis of PCa, and the elevated CXCL8 expression level was correlated with loss of AR expression." (PMID 36275733, 2022). "Changes in the function of AR signaling result in tumor suppression to tumor promotion, where the disease eventually progresses to the emergence of castration-resistant prostate cancer (CRPC)." (PMID 35800367, 2022). "At the CRPC stage where AR signaling is often still central to tumor growth, GATA2 continues to act as a crucial cofactor for AR transcriptional activity and colocalizes with both full-length AR and AR splice variants on the chromatin." (PMID 36212399, 2022). "We were the first to show differences in AR expression between different regions of the tumor in both men and women." (PMID 36361793, 2022). "The reported tumor suppressor function of GSK3β involves phosphorylation of the hinge and ligand binding regions of AR, resulting in decreased activation of AR gene targets and inhibition of cell proliferation." (PMID 35402240, 2022). "mTOR promotes AR receptor phosphorylation and activates AR transcription in a ligand-independent manner, and inhibition of mTOR reduces protein translation and prevents abnormal cell proliferation and tumor angiogenesis." (PMID 35886904, 2022). "Although abiraterone inhibits the enzyme CYP17A1 and blocks residual androgen synthesis and AR signaling, enzalutamide is a potent antagonist of AR that targets the AR signaling and the consequent tumor progression." (PMID 36078112, 2022). "In this part of the study, an AR cutoff value of 65% was selected, AR/ER and AR/PR cutoff values of 1.00 were selected, and a residual tumor Ki67 cutoff value of 20% was selected." (PMID 36556209, 2022). "AR expression was analyzed in individual tumor structures resected from GBM patients as well as on cells in an in vitro model mimicking the conditions prevailing in the tumor, i.e., hypoxia, nutrient deficiency, and necrosis." (PMID 36361793, 2022). "Recent discoveries suggested that AR retains a dominant role and acts as a stimulus to support tumor metastasis." (PMID 36127329, 2022). "Altogether, our findings suggest that MYC overexpression contributes to tumor initiation and progression by disrupting the AR transcriptional program." (PMID 35562350, 2022). "They then went on to show that enzalutamide treatment decreased growth in both ER+ and ER−/AR+ tumours, suggesting a role for antiandrogens in hormone resistant cancers." (PMID 36376977, 2022). "While lipid metabolism interacts with AR signaling, in addition it is closely involved in the regulation of the immune system in the tumor microenvironment." (PMID 36077824, 2022).